KL (klotho)
Diseases named in the same sentence as KL in open-access papers (continued):
Sharing a sentence is not in itself a finding about the gene and the disease.
renal fibrosis (continued). "Altogether our studies uncover a novel hypomethylating character of Rhein in preventing Klotho loss and renal fibrosis, and demonstrate the efficacy of Klotho-targeted epigenetic intervention in potential treatment of renal fibrosis-associated kidney diseases." (PMID 27703201, 2016). "In the case of renal fibrosis, decreased Klotho expression was associated with an increased Wnt signaling activation and subsequent activation of fibrogenic signaling pathways." (PMID 24987372, 2014). "Interestingly, rhein reversal of DNA hypermethylation-associated Klotho suppression ameliorates renal fibrosis, and it also provides renal protection through the regulation of DNA methyltransferases expression and methylation at the Klotho promoter." (PMID 40308781, 2025). "Hence, in this study involving 19-month-old mice subjected to 12 weeks of aerobic exercise, we observed a significant increase in Klotho expression within renal tissue, concomitant with improved renal fibrosis associated with aging." (PMID 39325739, 2024). "Renal fibrosis is associated with Klotho deficiency, and Klotho treatment could prevent fibrotic kidney changes in mice." (PMID 39089098, 2024). "In this study, we postulated that aerobic exercise may up-regulate Klotho expression to ameliorate age-associated renal fibrosis." (PMID 39325739, 2024). "The reduction in Klotho activity is associated with the potentiation of renal fibrosis." (PMID 39471136, 2024). "Downregulation or loss of renal klotho induces oxidative stress and renal fibrosis." (PMID 36977025, 2023). "In addition, Klotho can inhibit the renin-angiotensin-aldosterone system, and the nuclear factor kappa B (NF-κB) signaling pathway inhibits renal fibrosis caused by the inflammatory response." (PMID 35692408, 2022). "Targeting Klotho loss through HDAC3 inhibition may serve as a new strategy for anti-renal fibrosis therapies as well as promising therapeutic potential for a reduction in CKD progression." (PMID 35627181, 2022). "Despite NRF2 activation, in 18-month-old mice, klotho is further downregulated, NRF2 activation impaired, and pro-fibrotic gene expression and collagen deposition highly increased, in line with the role of klotho in diminishing cellular senescence and renal fibrosis, the hallmark of CKD." (PMID 35204184, 2022). "In consistence with our previous study, heart failure could cause renal fibrosis accompanied by Klotho depletion and β-catenin activation in the kidney." (PMID 33460402, 2021). "Whether the decrease of Klotho protein in the kidney is another cause of renal fibrosis or only a concomitant result needs more intervention experiments to determine." (PMID 33460402, 2021). "In addition, klotho is also involved in the inhibition of Wnt pathway-associated β-catenin activation, thus improving renal fibrosis." (PMID 32545510, 2020). "In addition, overexpression of Klotho can alleviate acute renal injury caused by cisplatin and renal fibrosis caused by unilateral ureteral obstruction." (PMID 30942135, 2019). "This suggests that Klotho deficiency might be involved in PBUT-induced renal fibrosis mediated via the ROS/NF-κB pathway." (PMID 30200452, 2018). "Klotho deficiency is relevant to renal fibrosis and podocyte injury in vivo and in vitro." (PMID 29590173, 2018). "Several animal models reported that klotho deficiency triggers renal fibrosis via inhibition of growth factors, enhanced endoplasmic reticulum stress, up-regulation of transient receptor potential channels, and up-regulation of the renin-angiotensin system (RAS)." (PMID 29590173, 2018). "This protective mode of action might also apply to renal fibrosis under other pathological conditions since Klotho promoter methylation is linked to uremic toxins and chronic kidney diseases." (PMID 27703201, 2016).
renal fibrosis (continued). "Furthermore, we provided clear evidence that Rhein reversal of Klotho loss through epigenetic DNA methylation closely correlates with the alleviation of renal fibrosis-associated kidney injury in a Klotho-dependent manner." (PMID 27703201, 2016). "Klotho is a putative aging suppressor, and there is compelling evidence that its depletion is associated with oxidative stress, inflammation, accelerated aging and renal fibrosis." (PMID 23967103, 2013). "Thus, Klotho is closely associated with inflammation, renal fibrosis, and kidney disease." (PMID 33767585, 2021). "At renal level, Klotho protein blocks various signaling pathways that lead to the development and maintenance of renal fibrosis after kidney damage in a mouse model." (PMID 39858242, 2025). "The recovery of Klotho, through recombinant protein delivery or plasmid expression, attenuated experimental renal fibrosis induced by AKI or CKD, demonstrating the therapeutic efficacy of Klotho restoration." (PMID 40362638, 2025). "It is known to be suppressed in renal diseases, including TIF and renal fibrosis, while increased expression or supplementation of Klotho has been shown to attenuate kidney fibrosis models." (PMID 39276250, 2025). "ROS overproduction is associated with reduced expression of klotho, a protective factor against CKD progression, and the development of chronic inflammation, a driver of renal fibrosis." (PMID 41295735, 2025). "In a rat model of unilateral ureteral obstruction (UUO), Klotho supplementation was found to reduce renal fibrosis." (PMID 40777989, 2025). "In general, the increase in Klotho improves renal fibrosis and recovery from acute kidney injury and reduces hypertension." (PMID 38169578, 2024). "IS and PCS decreased Klotho expression by enhancing DNA methylation of the Klotho gene in RTECs, thus promoting renal fibrosis." (PMID 38491448, 2024). "It has been shown that activation of Wnt/β-catenin protein promotes the development of renal fibrosis, and that Klotho is an endogenous antagonist of Wnt." (PMID 39325739, 2024). "For instance, administration of Klotho-derived peptide 1 via exogenous injection enhanced renal function, suppressed pro-fibrotic signaling pathways, restored endogenous Klotho expression, and mitigated renal fibrosis." (PMID 39325739, 2024). "In the UUO model, the HDAC3 inhibitor RGFP966 inhibits renal fibrosis by restoring KLOTHO expression through the inhibition of KLOTHO transcriptional regulators (Ncor and NF-κb)." (PMID 38929505, 2024). "miR-34a directly links to the 3′ UTR of Klotho mRNA, leading to the downregulation of Klotho that preserves the kidneys against severe and chronic failure, thus contributing to renal fibrosis." (PMID 38474021, 2024). "In mouse models, exogenous Klotho ameliorates vascular calcification, renal fibrosis, and cardiac hypertrophy." (PMID 38501099, 2024). "By elucidating the impact of YB-1 on epigenetic modifications, particularly its influence on Klotho methylation, and identifying shared molecular pathways, this study provides novel insights into the complex mechanisms driving renal fibrosis." (PMID 38474331, 2024). "Since Klotho was an essential endogenous inhibitor of renal fibrosis, we tended to evaluate the effect of aerobic exercise on klotho in mice with aging-induced renal fibrosis." (PMID 39325739, 2024). "In this study, we aimed to investigate the role and mechanism of Klotho in the improvement of renal fibrosis through aerobic exercise." (PMID 39325739, 2024). "Preventing the reduction of Klotho levels and enhancing its production can reduce renal fibrosis, slow down the progression of CKD, and improve mineral metabolism in CKD patients." (PMID 38501099, 2024). "In an aldosterone-induced CKD model, elevated HDAC1 expression inhibits H3K9 acetylation, leading to the downregulation of KLOTHO protein expression, which promotes renal fibrosis." (PMID 38929505, 2024).
renal fibrosis (continued). "Nevertheless, the role of exercise in ameliorating renal fibrosis via modulation of Klotho expression remains underexplored." (PMID 39325739, 2024). "Klotho is considered a negative regulator of renal fibrosis, with its overexpression and exogenous administration found to inhibit renal fibrosis development." (PMID 39325739, 2024). "Our findings suggest that aerobic exercise can inhibit the TGF-β1/Smad3 signaling pathway by modulating Klotho expression, thereby mitigate age-related renal fibrosis." (PMID 39325739, 2024). "YB-1 is a yet unreported essential part of the DNMT1–Klotho-dependent epigenetic cascade promoting renal fibrosis." (PMID 38474331, 2024). "A recent investigation demonstrated that a Klotho-derived peptide 1 in combating renal fibrosis by binding to TβR2, thereby disrupting the interaction between TGF-β and TβR2, suppressing fibroblast activation, and thwarting TGF-β-induced Smad2/3 activation." (PMID 39325739, 2024). "Rasal1 and Klotho are uniquely methylated in renal fibrosis, where Rasal1 and Klotho have been revealed to play a role in fibroblast proliferation and ECM production." (PMID 36864460, 2023). "Recently, researchers have found that klotho overexpression or exogenous supplement can alleviate renal fibrosis by suppressing epithelial-to-mesenchymal transition in cultured human renal tubular epithelial cells." (PMID 37261217, 2023). "In turn, the inhibition of miR-34a-mediated Klotho in tubular epithelial cells hampered the progression of renal fibrosis in a mouse model with UUO and the Adriamycin (ADR) nephropathy." (PMID 37760798, 2023). "It has been confirmed that the downregulation of Klotho in the renal tubular epithelial cells promotes renal fibrosis." (PMID 38132468, 2023). "In numerous experimental models, upregulating the soluble Klotho or the endogenous Klotho protected the kidney from injury, and inhibited renal fibrosis in CKD." (PMID 37228732, 2023). "Among them is mir-34a via downregulating klotho, an endogenous inhibitor of the renal fibrosis and activating TGF-β pathway that enhances EMT promoting the transition of the fibroblast into myofibroblast and increasing extracellular matrix deposition." (PMID 37631363, 2023). "Klotho protein protects the kidney by regulating the expression of fibrinogen and prevents renal fibrosis by inhibiting profibrotic signaling pathways (e.g., TGF-β/small mothers against decapentaplegic (Smad) and wingless/integrated (Wnt)/β-catenin." (PMID 37455912, 2023). "Under the guidance of Rasal1-sgRNA and KL-sgRNA, it rescued gene expression and alleviated renal fibrosis, which directly demonstrated the role of the KL gene in the maintenance of kidney function." (PMID 37008065, 2023). "Consistently, a recent study indicates that aberrant upregulation of miR-34a contributes to renal fibrosis progression though direct binding with the 3′UTR of Klotho, a key gene controlling aging." (PMID 35627181, 2022). "Klotho expression can be stimulated by reactivation of endogenous klotho or supplement of exogenous klotho, so as to improve renal fibrosis and reduce senescence." (PMID 36091755, 2022). "In a more specific way, a Klotho-derived peptide (30 amino acids) that inhibits TGF-β by binding to its receptor also protected against renal fibrosis." (PMID 35903083, 2022). "KP1 preserved kidney function, repressed TGF-β signaling, ameliorated renal fibrosis and restored endogenous Klotho expression." (PMID 35064106, 2022). "Initially, Klotho was found to ameliorate renal fibrosis; however, emerging evidence suggests that Klotho attenuates fibrosis in extra-renal tissues, such as pulmonary and cardiovascular systems." (PMID 35884879, 2022).
renal fibrosis (continued). "We demonstrated that pharmacological and genetic inhibition of HDAC4 largely attenuates renal fibrosis by suppressing several profibrotic signaling pathways, reducing renal injury, and retaining the Klotho expression." (PMID 35847036, 2022). "Klotho is a longevity gene with powerful kidney-protective effects such as anti-oxidation, anti-inflammation, anti-apoptosis, and suppression of renal fibrosis 1-4." (PMID 35165517, 2022). "Overexpression or supplementation of exogenous Klotho prevents nephropathy and attenuates renal fibrosis in various models of CKD18,24,25." (PMID 35064106, 2022). "Experiments in vivo and in vitro have validated that Huangkui capsules combined with metformin treatment effectively improved the weight, reduced blood glucose and ameliorated renal fibrosis via the Klotho/TGF-β1/p38 MAPK signalling pathway." (PMID 36187136, 2022). "Klotho defect leads to the increased cellular senescence and secretion of SASPs, aggravates renal fibrosis and promotes a variety of systemic phenotypes." (PMID 36091755, 2022). "Klotho administration promotes kidney healing and limits renal fibrosis in mice following ischemia-reperfusion injury, hence slowing the progression of AKI to CKD." (PMID 35509269, 2022). "In animal models of AKI, such as unilateral ureteral obstruction, restoration of Klotho can avoid renal fibrosis." (PMID 35056905, 2021). "To identify the effects of Klotho on renal fibrosis, we delivered the plasmid pV5‐sKlotho for secreted Klotho into UIRI mice through hydrodynamic‐based gene delivery, an approach that is commonly used to ectopically express proteins in liver and kidneys." (PMID 33463897, 2021). "Overexpression of miRNA‐34a promotes epithelial‐to‐mesenchymal transition (EMT) in human renal tubular epithelial HK‐2 cells, together with down‐regulation of Klotho, which is an endogenous antagonist of renal fibrosis." (PMID 33438362, 2021). "Downregulation or deficiency of Klotho, the co-receptor of FGF23, promotes oxidative stress and renal fibrosis." (PMID 33460402, 2021). "This suggests that genistein-induced Klotho restoration in the kidney is essential for the restoration of renal fibrosis function." (PMID 34209224, 2021). "Curcumin attenuated cyclosporine induced renal fibrosis by enhancing Klotho expression and inhibiting TGF-b signaling." (PMID 34869655, 2021). "Our previous report found that the preventative effects of Klotho against renal fibrosis are partially attributable to the downregulation of Egr-1 expression by inhibiting TGF-β1/Smad3 signaling in high-glucose-treated human MCs13." (PMID 32054986, 2020). "In contrast, overexpression of Klotho significantly inhibited renal fibrosis and cardiomyocyte hypertrophy induced by IS in mice." (PMID 32464602, 2020). "We found that Klotho suppressed the IS-induced inflammatory response to protect against renal fibrosis and cardiac hypertrophy." (PMID 32464602, 2020). "Activation of Klotho has been reported to reduce levels of oxidative stress, improve mitochondrial function, reduce renal fibrosis, and inflammatory burden." (PMID 32982966, 2020). "In renal tubules, Klotho is involved in cell senescence, anti-oxidant response, and renal fibrosis, thus regulation of its expression is critical to understand its roles in renal diseases." (PMID 32571212, 2020). "Pre-clinical studies have indicated that administration of soluble Klotho can reduce renal fibrosis, VC, and EMT." (PMID 32982966, 2020). "As reduced Klotho expression was observed in renal fibrosis, we wondered the effects of Sp1 knockdown on renal fibrosis markers." (PMID 32571212, 2020). "It is noteworthy that Klotho is predominantly expressed in RTECs where it regulates senescence, tumor growth, and renal fibrosis." (PMID 32571212, 2020). "A previous study showed that renal fibrosis caused by a unilateral ureteral obstruction in mice resulted in increased levels of TGF-β1, α-SMA, and fibronectin, as well as a reduced level of klotho." (PMID 32942691, 2020).
renal fibrosis (continued). "Similar to the NRF2 system, klotho is repressed in CKD, and stimulation of klotho can ameliorate oxidative stress and mitochondrial function, renal fibrosis, inflammation, as well as premature ageing, including EVA." (PMID 32260373, 2020). "In contrast, supplementation with Klotho in these two models inhibits renal fibrosis by intercepting Wnt/β-catenin signaling." (PMID 33362554, 2020). "This study aimed to evaluate repression of Klotho on unilateral ureteral obstruction (UUO)-induced renal fibrosis and endothelial-to-mesenchymal transition (EndoMT) in mice." (PMID 31024315, 2019). "Our findings demonstrated that Klotho significantly ameliorated EndoMT progression by targeting TGF-β1/Smad/Snail1 signaling in UUO mice, which provides the possibility for Klotho-based therapeutic protection against renal fibrosis." (PMID 31024315, 2019). "We observed that Klotho strongly protects against d‐gal‐induced renal fibrosis and mitochondrial dysfunction." (PMID 31318148, 2019). "We demonstrated exogenous Klotho supplement attenuated renal fibrosis by regulating TGF-β1-induced EndoMT." (PMID 31024315, 2019). "Soluble klotho also inhibited TGF-β-induced renal fibrosis and metastasis and blocked the levels of the inflammatory proteins TNFα and IFNγ." (PMID 31581134, 2019). "The results highlight the potential of soluble klotho as a biomarker of renal fibrosis and podocyte injury in humans." (PMID 29590173, 2018). "Subsequent data also indicated that Klotho inhibits transforming growth factor β1 (TGFβ1)–induced cell migration in renal fibrosis." (PMID 29928482, 2018). "For this reason, KL has been further investigated in animal and in vitro models to determine if KL promoter hypermethylation is involved in the development of CKD and altered renal fibrosis was noted in cells with KL hypermethylation." (PMID 30359254, 2018). "For example, the administration of soluble klotho protein significantly attenuated UUO-induced renal fibrosis and suppressed the expression of fibrosis markers and TGF-β1 target genes, such as Snail and Twist." (PMID 30348110, 2018). "Here, we discuss in detail the role and pathophysiological implications of klotho in ion disorders, the inflammation response, vascular calcification, mineral bone disorders, and renal fibrosis in CKD." (PMID 30348110, 2018). "Urinary angiotensinogen levels were also evaluated to explore the role of RAS with soluble klotho in renal fibrosis." (PMID 29590173, 2018). "We report that serum and urinary klotho levels are strongly correlated with renal fibrosis and foot process effacement of podocyte, respectively." (PMID 29590173, 2018). "Recently study also shows that Nrf2 can restore the klotho expression and protect against renal fibrosis." (PMID 29973206, 2018). "Our data suggested that soluble serum and urinary klotho levels represent a potential biomarker to predict renal fibrosis and podocyte injury in humans." (PMID 29590173, 2018). "Administration of secreted klotho or genetic manipulation induces klotho overexpression to ameliorate renal fibrosis." (PMID 29590173, 2018). "The results showed that siRNA Klotho-treated mice displayed slight increase of renal fibrosis, phosphorylated Smad3 and reduced BMP-7." (PMID 28387374, 2017). "To date, several factors, such as hepatocyte growth factor and Klotho, have been reported to have a therapeutic potential for renal fibrosis by reducing fibrogenic cytokine production as well as fibronectin and type I collagen deposition." (PMID 28585867, 2017). "This study showed HRS is able to promote renal function recovery after IR injury in mice by increasing Klotho expression, activating autophagy and inhibiting renal fibrosis." (PMID 28848432, 2017). "Treatment with huMSCs ameliorated long-term kidney function after IRI, minimised renal fibrosis, decreased β-galactosidase expression and increased the expression of Klotho." (PMID 28129785, 2017).